LARP1 (La ribonucleoprotein 1, translational regulator)
Diseases named in the same sentence as LARP1 in open-access papers (continued):
Sharing a sentence is not in itself a finding about the gene and the disease.
cancer (continued). "As emerging research uncovers the function of each LARP, it is evident that La, LARP1, LARP6, LARP7 and possibly LARP4a and 4b are dysregulated in cancer." (PMID 26501340, 2015). "Therapies to attenuate pathological upregulation of La, LARP1 or LARP6 are likely to have profound anti-proliferative and pro-apoptotic effects in cancer cells." (PMID 26501340, 2015). "LARP1 protein expressed was higher in all six HCC samples, displaying more than 3-fold increase of LARP1 expression as compared that in the adjacent non-cancer tissue samples." (PMID 24159927, 2013). "Given the involvement of LARP1, CNBP, AUF1 and TIAR1 in 5′-TOP mRNA regulation and the largely unexplored nature of their regulatory networks, it is plausible that Ephexin1 coordinates with these proteins to modulate the translation of cancer-specific mRNAs." (PMID 40855114, 2025). "So, unlike those showing LARP1 negatively regulates translation under the control of mTORC1, we have consistently seen the opposite in cancer cells, using methionine uptake, SILAC and SUnSET assays." (PMID 32233986, 2021). "As LARP1 is known to play a crucial role in permitting continued translation and cancer cell survival under stress, it is possible that this ‘non-TOP role’ of LARP1 is driven by stress conditions." (PMID 32233986, 2021). "This suggests that in certain cancer cells at least, under both non-stressed and stressed conditions, LARP1 is not in complex with RAPTOR." (PMID 32233986, 2021). "We established that LARP1 exerts this pro-survival effect, at least in part, by post-transcriptionally promoting the expression of BCL2, a well-characterized oncogenic anti-apoptotic protein and a promoter of cancer cell survival." (PMID 26717985, 2016). "Here we speculate on a model whereby LARP1 acts as an mTORC1-dependent regulator of TOP mRNA translation in non-malignant cells but as a constitutive activator of TOP and pro-survival mRNA translation in the cancer cells in which it is upregulated." (PMID 32233986, 2021). "Moreover, we show that the regulatory activity of LARP1 is not just confined to mTOR, but that LARP1 is complexed to many other mRNA transcripts involved in cancer-related functions." (PMID 25531318, 2015). "However, more regulator genes negatively related to those compounds, like AGO2, DCP2, EIF3D, EIF4E, LARP1, and NCBP3 (related to 30 cancer drugs both in GDSC and CTRP), indicating the patients with higher mRNA expression level of these regulator genes might sensitive to these compounds." (PMID 36092891, 2022). "This implies that LARP1 has a distinct interactome in cancer compared to non-malignant cells that could result from conformational changes to LARP1 driven by upstream signalling events, partner protein interactions or associations with other RBPs, micro or non-coding RNAs." (PMID 26501340, 2015). "Screening these candidate miRNAs for expression correlation in HNSCC via the Pan-cancer subproject of the ENCORI database revealed significant negative correlations in 13 EIF1-miRNAs, 21 LARP1-miRNAs, and 1 METTL1-miRNA interactions." (PMID 40018039, 2025). "Unlike La, LARP1 and LARP6, knockdown of LARP4a in cancer cells promotes rather than inhibits cancer cell migration." (PMID 26501340, 2015). "In developing this review, the authors came to an intriguing conclusion: LARP1 exhibits distinct mechanisms for binding TOP and non-TOP mRNAs that may be perturbed in cancer cells." (PMID 32233986, 2021).
tumor (35 papers, 2013 to 2025). "Immune infiltration analysis and transcriptomic data also revealed significant associations between LARP1 and immune cell infiltration in the tumor microenvironment, as well as tumor progression, enhancing its reliability as a potential oncogene." (PMID 40018039, 2025). "In our preliminary bioinformatics analysis, LARP1 was found to be significantly associated with tumor progression, with higher expression levels observed in HNSCC." (PMID 40018039, 2025). "As well as a role in regulating key CSC-associated traits such as clonogencity, tumour-initiating capability and chemotherapy resistance, LARP1 is required to maintain CD133+ and Aldefluorbright putative CSC-like populations." (PMID 26717985, 2016). "The reduced growth potential of Larp1 loss-of-function mutants may also underly Larp1’s reported role as an oncogene in some tumor models." (PMID 41278816, 2025). "In addition, the expression level of LARP1 was significantly associated with tumor size, TNM stage, and lymph node metastasis in patients with PTC." (PMID 35264065, 2022). "While, in the contrast with previous findings, our results implicated that LARP1 exerts its tumor suppressive effect in ccRCC cellular progression, which might owe to the timepoint-dependent feature of LARP1 knockdown." (PMID 33680937, 2020). "For example, aberrant expression of HuR links to tumor hypoxia, chemotherapy resistance, and radioresistance, while LARP1 serves as an oncogenic protein to promote tumor survival and progression." (PMID 41285712, 2025). "We further explored LARP1’s role in the tumor immune microenvironment, including its potential impact on immune cell recruitment and immune suppression." (PMID 40018039, 2025). "As an RNA-binding protein, LARP1 is involved in regulating various cellular processes and has been shown in multiple studies to play a crucial role in tumor cell migration, proliferation, and invasion, particularly during tumor metastasis." (PMID 40018039, 2025). "Pearson correlation was calculated for the expression levels of the gene pairs – FER and mTOR and FER and LARP1 in both tumor and healthy tissues." (PMID 39206154, 2024). "LARP1 knockdown abolished cell proliferation, triggered cell apoptosis in vitro as well as prohibited tumour growth in vivo, whereas LARP1 overexpression incited HB progression." (PMID 37070251, 2023). "Accumulating studies have shown that La‐related protein 1 (LARP1) is involved in the occurrence and development of various tumours." (PMID 37070251, 2023). "In vivo xenograft studies indicated that the sh‐LARP1#1 group's tumour had lower volume and weight than those in the sh‐NC group." (PMID 37070251, 2023). "The results of an orthotopic mouse model showed that the livers of HuH6/LARP1‐WT mice had more tumour foci than those of the HuH6/LARP1‐MUT group (median survival, 34 days and 42 days, respectively; p = .041)." (PMID 37070251, 2023). "Circ-CCDC66 promoted PTC proliferation, migration, invasion, and tumor growth by sponging miR-129-5p and promoting LARP1 expression." (PMID 35264065, 2022). "This is in keeping with clinical data showing elevated levels of LARP1 protein in tumour cells correlate with poorer patient survival and (in-vivo) lower sensitivity to chemotherapy." (PMID 32233986, 2021). "Spearman statics results suggested that the expression of ASB16-AS1 was strongly correlated with LARP1 expression in ccRCC tumor tissues." (PMID 33680937, 2020). "The expression of LARP1 significantly decreased in ccRCC tumor tissues compared with its adjacent normal tissues." (PMID 33680937, 2020). "As before, there was a striking difference in tumour volumes between control and LARP1-knockdown tumours." (PMID 26717985, 2016). "When 106 cells were injected, all mice developed bilateral tumours, though the median latency was considerably greater for tumours with LARP1 knockdown compared to controls (19 versus 11 days, respectively; P = 0.011)." (PMID 26717985, 2016).
tumor (continued). "Tumour latency was more pronounced, with a median time to tumour development of 22 days in control cells, and 42 days in cells with LARP1-silencing (P < 0.001)." (PMID 26717985, 2016). "The LARP1 protein levels of tumor tissue specimens were significantly higher than those of the adjacent normal mucosa tissue." (PMID 27614686, 2016). "The result showed that tumor depth, AJCC stage, LNM stage, distant metastasis, vascular invasion, and expression of LARP1 and PCNA were associated with decreased OS; all these characteristics, except tumor depth, were associated with decreased DFS." (PMID 27614686, 2016). "Quantitative real-time polymerase chain reaction and Western blot analyses were carried out to determine the mRNA and protein expression of LARP1 in CRC tumor tissues and paired adjacent normal mucosa." (PMID 27614686, 2016). "La, LARP1 and LARP6 are upregulated and associated with tumour invasion and migration whereas LARP7 and possibly LARP4a are down-regulated in malignancy and associated with progression and metastasis." (PMID 26501340, 2015). "LARP1 overexpression resulted in significantly more rapid tumor growth, with a mean final tumor volume of 162.8 mm3, compared to 51.0 mm3 in the control group." (PMID 25531318, 2015). "In the clinical subgroup with one single HCC tumor nodule, the 5-year survival rates were 63% and 9%, respectively, for low - or high -LARP1 expression patients (P < 0.01)." (PMID 24159927, 2013). "Spearman analysis revealed correlations between LARP1 and Tumor size (P P < 0.05), survival time (P < 0.01), Child-Pugh (P < 0.01) and vital status (P < 0.01)." (PMID 24159927, 2013). "In our univariate analysis, stepwise inclusion of variables in the model showed that significant prognostic factors included LARP1 level, tumor size, tumor number, Child-Pugh class and TNM classification." (PMID 24159927, 2013). "Furthermore, survival analysis demonstrated a significant correlation, with high expression of LARP1 associated with poorer overall survival (HR = 1.422, p = 0.0105), further supporting the close relationship between LARP1 and tumor prognosis." (PMID 40018039, 2025). "Additionally, LARP1 is experimentally validated as a key promoter of HNSCC progression by enhancing tumor cell proliferation, migration, and invasion." (PMID 40018039, 2025). "Additionally, LARP1 overexpression significantly increased cell proliferation in vitro and promoted tumour growth in vivo." (PMID 37070251, 2023). "In addition, we revealed that O‐GlcNAcylation at S672 of LARP1 plays an important tumour‐promoting role in HB by preventing its degradation." (PMID 37070251, 2023). "The volume and weight of LARP1‐S672A tumours were markedly lower than those in the LARP1‐WT group." (PMID 37070251, 2023). "The abnormal expression of LARP1 was highly related to tumor occurrence and metastasis." (PMID 35365169, 2022). "However, LARP1 inactivation paradoxically decreases growth rate in at least some tumours and potentially contributes to 5q syndrome, a myelodysplastic disorder with parallels to ribosomopathies caused by loss-of-function mutations in core ribosomal proteins." (PMID 32233986, 2021). "Furthermore, the expression ASB16-AS1 and LARP1 in ccRCC tumor tissues were suggested strongly correlated." (PMID 33680937, 2020). "As LARP1 is highly expressed in multiple epithelial cancer types, its upregulation may represent a common feature of tumor progression." (PMID 25531318, 2015). "To investigate whether LARP1 regulates tumorigenicity in vivo we assessed the tumor-forming ability of control and LARP1-overexpressing HeLa cells." (PMID 25531318, 2015). "LARP1 is highly expressed in HCC than in adjacent non-tumor tissues." (PMID 24159927, 2013). "LARP1 expression was correlated to survival time, vital status, tumor size and Child-Pugh score." (PMID 24159927, 2013). "And the LARP1 expression of adjacent non-tumor tissues was lower in the healthy persons." (PMID 24159927, 2013).
tumor (continued). "The meaning of the decrees of LARP1 in adjacent non-tumor tissues is wildly unknown and more deeper research needed to clarify the mechanism of LARP1 in HCC develop." (PMID 24159927, 2013). "Moreover, multivariate analysis demonstrate that tumor size, tumor number, Child-Pugh class and LARP1 expression level are indeed predictive of the overall survival (OS) of HCC patients." (PMID 24159927, 2013). "After the SH intervention, the levels of the tumor angiogenesis-related genes MMP-2, VEGFA, VEGFC, VAV2, and LARP1 were significantly downregulated when compared with the Model group, whereas the GADD45A level was markedly upregulated." (PMID 41444284, 2025). "In future studies, we plan to investigate the synergistic effect of LARP1 with other known prognostic molecules (such as EIF3D, EIF1, METTL1) in HNSCC, particularly their potential interactions in tumor cell growth, metastasis, and immune evasion." (PMID 40018039, 2025). "Multivariate Cox regression analysis revealed that age, metastasis, pre‐treatment extent of tumour (PRETEXT) and LARP1 mRNA levels were independent prognostic indicators of OS." (PMID 37070251, 2023). "The expression of CNV-amplified m7G regulators was markedly higher in HCC specimens than in normal control specimens, such as AGO2, NCBP2, GEMIN5 and LARP1, while the expression of EIF4E3 was significantly lower in tumor specimens." (PMID 36389726, 2022). "More than half of the m7G-related genes were significantly upregulated in tumor samples, such as METTL1, WDR4, EIF4E, LARP1, and LSM1." (PMID 36761423, 2022). "The protein expressions of METTL1, NSUN2, EIF4G3, LARP1, NCBP1, and NCBP2 were higher in tumor tissues than in normal tissues; however, the protein expressions of WDR4, EIF4E1B, and NCBP2L were negative in both tumor and normal tissues." (PMID 35785179, 2022). "In our study, we found high expression of EIF4E1B, LARP1, GEMIN5, and DCP2 in tumor tissues, which seems to be consistent with our results." (PMID 36003341, 2022). "We observed DHX9 and MATR3 (in Tumor A, set 1), HNRNPC and LARP1 (in Tumor A, set 2), SRSF1 (in Tumor B, set 1 & Tumor B, set 2), SRSF6 and IGF2BP2 (Tumor B, set 2), HNRNPU (in Tumor B, set 2 & Tumor C, set 2), and FAM120A and HNRNPA2B1 (in Tumor C, set 2)." (PMID 31892958, 2020). "Additionally, quantitative immunohistochemical analysis revealed that the expression of EIF3D, EIF1, LARP1, and METTL1 in the tumor group was significantly higher than in adjacent tissues." (PMID 40018039, 2025). "In addition, knockdown of LARP1 suppressed the proliferative, migratory, and invasive capacities of PTC cells as well as PTC tumor growth in a mouse xenograft model." (PMID 35264065, 2022). "It should be underlined however that upstream regulators analysis indicated that LARP1 –mediated pathway is rather inhibited in the center of ADC tumor (negative z-score for center vs. control comparison)." (PMID 35512017, 2022). "Moreover, LARP1 overexpression effectively alleviated the enhancement of downregulated ASB16-AS1 on the EMT phenotype both in 786-O cells and xenograft tumor tissues." (PMID 33680937, 2020). "In our validation cohort, early-stage (TNM stages I-II, tumor size less than 3 cm, single tumor nodule) HCC patients with low level of LARP1 protein immunostained also display a relative high OS than those diagnosed with late-stage HCC who carry high levels of LARP1 expression." (PMID 24159927, 2013). "Notably, mRNA levels of LARP1, METTL1, WDR4, and NCBP1 were upregulated in tumor specimens." (PMID 40485623, 2025). "In another group of HCC patients whose survival has been difficult to predict in the clinic, namely, those with tumor sizes smaller than 3 cm in diameter, the 5-year survival rate was 75% in the low LARP1 group, as opposed to 23% for patients exhibiting high LARP1 expression (P = 0.005)." (PMID 24159927, 2013).
infection (7 papers, 2016 to 2025). The state of being infected such as from the introduction of a foreign agent such as serum, vaccine, antigenic substance or organism. "Furthermore, gradient transfection of LARP1-Flag showed that increased LARP1 expression reduced the cytopathic effect (CPE) caused by infection, as observed under bright-field microscopy." (PMID 40294010, 2025). "Studies have shown that LARP1 interacts with viral RNA and affects viral replication in infections such as hepatitis C virus (HCV), dengue virus (DENV), and SARS-CoV-2, but its role in EV-D68 infection remains unexplored." (PMID 40294010, 2025). "RD cells were transfected with PABPC1-Flag or LARP1-Flag plasmids, followed by infection with EV-D68, and the cells were collected for immunoblotting and viral titer analysis." (PMID 40294010, 2025). "To mimic the natural cleavage product of LARP1 generated during EV-D68 infection, we constructed the ΔN1–371 truncation mutant, retaining the C-terminal portion (N372-1019)." (PMID 40294010, 2025). "This also explains why EV-D68 cleaves LARP1 during infection." (PMID 40294010, 2025). "Immunoblotting revealed that mTOR and p-mTORS2448 levels were significantly reduced upon EV-D68 infection, suggesting that EV-D68 impairs mTOR signaling, which may contribute to increased LARP1 binding to viral RNA while potentially affecting LARP1 activation." (PMID 40294010, 2025). "Therefore, our data expand the role of LARP1 as an HCV host factor that is most prominently involved in the early steps of infection, likely contributing to endocytosis of viral particles through the pleiotropic effect LARP1 has on the cellular translatome." (PMID 38636657, 2024). "Given the fact that both PABPC1 and LARP1 have RNA-binding activity, one could envisage that RyDEN may associate with DENV RNA through its interaction with these proteins during infection." (PMID 26735137, 2016). "Interestingly, while LARP1 protein levels decreased, LARP1 mRNA levels increased in response to infection, suggesting that the host may upregulate LARP1 transcription in response to protein cleavage." (PMID 40294010, 2025). "Since LARP1 intriguingly concentrates at the ER and in the proximity of lipid droplets, an important viral budding site, upon infection, we tested whether accumulation of Netrin-1 in microsomes could foster increased morphogenesis, through the evaluation of the specific infectivity of virions." (PMID 27031829, 2016). "To explore the effects of PABPC1 and LARP1 on viral replication, we overexpressed PABPC1-Flag or LARP1-Flag in RD cells, followed by infection with EV-A71 or CV-A16." (PMID 40294010, 2025). "To determine whether LARP1 interacts with EV-D68 RNA during infection, we transfected HEK293T cells with LARP1-Flag plasmid, infected them with EV-D68, and performed RNA immunoprecipitation (RIP) to detect RNA binding efficiency." (PMID 40294010, 2025). "The functional interaction of RyDEN with cellular mRNA-binding proteins PABPC1 and LARP1 prompted us to test whether RyDEN was recruited to DENV RNA during infection." (PMID 26735137, 2016).
cardiovascular disease (1 paper, 2021). "We predicted 6 candidate genes (PANK1, TRIB1, BMPR2, HDAC9, THBS1, and LARP1) that might bind to miR-942-5p and played a role in cardiovascular disease." (PMID 33869307, 2021).
LARP1 also shares sentences with these, for which no sentence is quoted: endometrial carcinoma (2 papers); glioma (2); Alzheimer disease (1); autism (1); endometrial adenocarcinoma (1); genetic disorders (1); head and neck squamous cell carcinoma (1); intrahepatic cholangiocarcinoma (1); leukaemia (1); macrocytic anemia (1); nonalcoholic steatohepatitis (1); stomach cancer (1); T cell acute lymphocytic leukemia (1); thyroid abnormality (1); undifferentiated thyroid carcinoma (1).